SPATA32 (spermatogenesis associated 32)
Synonyms: C17orf46; TEX34; FLJ25414; AEP2; VAD1.2
Tractability: PROTAC: ubiquitination databases record sites on it.
Gene: Protein-coding gene on chromosome 17 (45,254,393 to 45,262,094, reverse strand). Ensembl gene ENSG00000184361.
Gene Ontology:
Molecular function: protein binding; actin binding
Biological process: spermatogenesis
Cellular component: perinuclear region of cytoplasm
Genetic constraint (gnomAD): Loss-of-function variants: 29 observed, 36.58 expected, observed/expected ratio (o/e) 0.79, 90% interval 0.59 to 1.08. The upper end of that interval is the gene's LOEUF score, 1.08, which puts it in group 4 of 6, group 1 being the genes least tolerant of losing a copy. Missense variants: 409 observed, 497.67 expected, observed/expected ratio (o/e) 0.82, 90% interval 0.76 to 0.89. Synonymous variants: 168 observed, 207.14 expected, observed/expected ratio (o/e) 0.81, 90% interval 0.71 to 0.92.
Homologues: Orthologues: chimpanzee SPATA32 (98% identical), macaque SPATA32 (84% identical), mouse Spata32 (35% identical), rat Spata32 (33% identical).